MIR4723 (microRNA 4723)
Synonyms: hsa-mir-4723; mir-4723
Gene: MicroRNA gene on chromosome 17 (28,360,654 to 28,360,734, forward strand). Ensembl gene ENSG00000284532.
Homologues: Orthologues: chimpanzee MIR4723 (100% identical).